MIF (macrophage migration inhibitory factor)
Diseases named in the same sentence as MIF in open-access papers (continued):
Sharing a sentence is not in itself a finding about the gene and the disease.
tumor (continued). "Mechanistically, overexpression of MIF in NSCLC increases the phosphorylation level of JNK, c-Jun, and subsequent activity of the transcription factor AP-1 in a CD74-dependent manner, which promotes tumor angiogenesis by increasing expression of the angiogenic factors CXCL8 and VEGF." (PMID 35842634, 2022). "MIF also induces NF-κB activation through interactions with CD74 and enhances NF-κB target gene expression, including cellular inhibitors of apoptosis 2 (c-IAP2), Bcl-xl, MMP-2, uridylyl phosphate adenosine (uPA) and HIF-1α, facilitating the proliferation and migration of tumor cells." (PMID 35842634, 2022). "TA-MSCs, TA-MSCs-EVs and MIF mainly promote the recruitmention in TME, survival and secretory function of neutrophils, which not only inhibits the spontaneous apoptosis of neutrophils but also suppresses the killing of tumor cells by other anti-tumor immune cells." (PMID 35842634, 2022). "Besides, MIF-EGFR/TNFRSF14, IGF1/2-IGF1R/2 R, TNFSF12-TNFRSF12A (TWEAK-Fn14) interactions also mediated the crosstalk between TPF or SLF with EPCs, consistent with their function in facilitating tumor progression." (PMID 36198671, 2022). "Taken together, upregulation of miR-451a inhibited cell proliferation and induced apoptosis in NOZ and TGBC2TKB cells, partly through regulation of MIF, PSMB8 and CDKN2D, suggesting that miR-451a has a tumor-suppressing role and could be a novel therapeutic target in GBC cells." (PMID 34112884, 2021). "Therefore, novel, clinically relevant Hsp90 inhibitors provide therapeutic selectivity by interfering with tumorigenic MIF in tumor epithelial cells but not in normal cells." (PMID 33542244, 2021). "It demonstrated that MIF as a proinflammatory cytokine may actively participate in stimulating signal transduction pathways involved in EMT, controlling the acquisition of invasiveness features by tumor cells and facilitating metastasis processes." (PMID 34157052, 2021). "Intriguingly, the tumor types that responded best to Imalumab were immune responsive tumors like NSCLC, ovarian, and esophageal-perhaps supporting the possibility that neutralizing MIF therapies may provide immunotherapeutic protections." (PMID 33324425, 2020). "Furthermore, when MIF was depleted using an established neutralizing anti-MIF antibody 5-days post tumor implantation there was no survival benefit." (PMID 32625208, 2020). "Finally using a in vivo xenograft tumour model in nude mice, we showed that ISO-1 treatment resulted in significant reduction in PANC-1 cell-induced tumour growth with concomitant reduction in MIF expression in tumour tissues." (PMID 32317702, 2020). "If such an approach could regulate MIF’s immunosuppressing activity and pro-inflammatory arrangements, this would provide a therapeutic strategy if we only prevent CD74 function in antigen presentation to the immune cells in the tumor milieu." (PMID 33327409, 2020). "Together, the data suggest that circulating MIF of non-tumor origin might promote tumor angiogenesis, thereby promoting overall tumor growth in vivo." (PMID 31664114, 2019). "We evaluated tumor development in the complete absence of MIF." (PMID 31360118, 2019). "In order to confirm that T cells are required for control of MIF KD tumors, we performed a T cell depletion experiment by treating WT and MIF KD 4T1 tumor-bearing mice with CD4 and CD8 depleting antibodies or isotype control antibodies (cIgG) throughout the course of tumor growth." (PMID 29864117, 2018). "In addition, since MIF expression is absent in the whole animal rather than just in the tumor, it is not possible to determine the role of tumor cell-derived MIF using this model." (PMID 29864117, 2018). "However, this study focused on tumor-infiltrating MDSCs in late-stage 4T1 tumors, and we do not see a MIF-dependent difference in MDSCs at the early time points used in the current study." (PMID 29864117, 2018).
tumor (continued). "Within the tumor microenvironment, TAMs are forced forwards M2 phenotypes by GBM cells via secreting a wide variety of factors such as IL10, IL4, IL6, M-CSF, macrophage inhibitory factor (MIF), TGFβ, and prostaglandin E2 (PGE2), and subsequently support tumor growth and invasion." (PMID 29132376, 2017). "Cell biological experiments were also performed on NSCLC cell lines to confirm the tumor-suppressive role of miR-451 and whether or not MIF is targeted by miR-451." (PMID 28704499, 2017). "Therefore, the MIF expression levels that originated from CRC cells or from other undefined cells in the primary tumor microenvironment did not appear to have an important prometastatic effect." (PMID 26087187, 2015). "MIF was secreted from many kind of cells within tumor tissues, including activated lymphocytes, macrophages, and tumor cells; these cells may produce high levels of MIF as is noted in HCC cases." (PMID 21438767, 2011). "MIF expression showed positive correlations with progesterone (p = 0.006) and estrogen (p = 0.028) receptor expression, markers of a favourable prognosis and a negative correlation to tumour size (p = 0.007)." (PMID 19602265, 2009). "Notably, these findings suggest that MIF+ tumor cells infiltrating TLS, rather than TLS status alone, may serve as a co-factor for evaluating immunotherapy response, a phenomenon detectable even in baseline tumors of ESCC non-responders." (PMID 41355948, 2026). "In our scRNA-seq dataset, tumor cells had the highest expression of MIF and MDK, while other populations, such as monocytes/macrophages, had only low expression, suggesting that tumor cells may be the major source of MIF and MDK affecting lymphocyte cytotoxicity." (PMID 39908652, 2025). "Secreted cytokines (MIF/CSF1) mainly target C1QC+TAMs to impede the antitumor immune effects of TAMs rather than those of SPP1+TAMs, suggesting that anti-CSF or MIF treatments may be insufficient to deplete macrophage subgroups with tumor growth-promoting potential." (PMID 39323622, 2024). "However, interactions involving TAMs signalling to malignant cells expressing CD44 via SPP1 and MIF, known to suppress T‐cell activation and promote TAM secretion of growth factors respectively, decreased after therapy, suggesting a transformation towards an anti‐tumour microenvironment." (PMID 39415331, 2024). "The high concentrations of RANKL, macrophage migration inhibitory factor (MIF), and osteoprotegerin (OPG) in the peripheral blood of patients may contribute to the process of intravasation, angiogenesis, survival, and epithelial-mesenchymal transition of circulating tumor cells." (PMID 37153744, 2023). "We then discussed the effects of other cell types on epithelial cells in tumor tissue, and the results indicated that immune cells could regulate epithelial cells through specific ligand–receptor pairs, such as TNFSF14-TNFRSF14, MIF-(CD74+CD44), IFNG-(FINGR1+IFNGR2), CXCL12-ACKR3, and CXCL11-ACKR3." (PMID 36569924, 2022). "In the specific setting of non-small cell lung cancer (NSCLC), monocyte-derived macrophage secretion of MIF is augmented by NSCLC cells, and secretion of MIF may contribute to local angiogenic activity and tumor metastasis in cell culture models and mouse models of tumor development." (PMID 23522304, 2013). "Consistent with experimental models, liver tissues from MASLD patients with hepatic metastases exhibited significant upregulation of MIF in non-tumoral parenchyma and CD44 expression in tumor cells." (PMID 41545340, 2026). "In this research, no statistical differences in the expression levels of MIF, CD74, and CXCR4 were found between tumor and normal groups." (PMID 40066443, 2025). "Furthermore, widespread co-localization of MIF-(CD74+CXCR4) was observed in spatial transcriptomics, suggesting that the MIF signaling pathway may be a key mechanism through which MVI_Scissor+ malignant cells exert significant influence in the tumor microenvironment." (PMID 39176099, 2024).
tumor (continued). "Tissues from patients with low numbers of CD4+ T cells within 20 μm of the tumor secreted less MIF and there was a negative correlation between MIF levels and numbers of CD4+ T cells within and 20 μm of the tumor nests." (PMID 35954489, 2022). "Both CM presented proteins involved in proliferation of both tumor and non-tumor cells, of which CAPN1, CST1, LAMC2 and RANBP3 stood out in CM3D and GPC6, ILK, MAPK1, MIF and PICALM in CM2D." (PMID 34884877, 2021). "Our data suggest that MIF increases CRC growth and supports tumor-specific macrophage recruitment, tumor cell proliferation, and neoangiogenesis without affecting overall inflammation in established tumors." (PMID 33542244, 2021). "In contrast, granulocytic MDSCs (G-MDSCs) expressed high levels of the MIF non-cognate receptor CXCR2 and showed minimal accumulation in the tumor microenvironment." (PMID 32625208, 2020). "The refametinib/4‐IPP combination significantly induced regression of tumor growth of KRAS mutant CRCs, while the MEK inhibitor or MIF alone with small molecules did not influence tumor growth." (PMID 29896883, 2018). "So MIF derived from CRC cells, or some other undefined cells in primary tumor microenvironment, did not play a prometastatic effect." (PMID 26087187, 2015). "However, the role of D-DT, as opposed to MIF, in tumor biology remains unknown." (PMID 24406307, 2014). "High expression levels of MIF in tumor cells were not correlated with clinicopathological variables, whereas high expression levels of CXCR4 in tumor cells were positively closely correlated with T status (P = 0.045) and clinical stage (P = 0.044)." (PMID 23497377, 2013). "Interestingly, MIF and DDT often play similar roles in tumor progression, independent of the cancer type." (PMID 36672343, 2023). "EGLN1, MIF, PANX1, and RRM2 had higher expression in tumor than in normal samples." (PMID 35311093, 2022). "On the other hand, the correlations of MIF scores with CD68, CD11c and CD163 scores in tumor nest and tumor stroma of NPC patients showed no statistical significance, suggesting that MIF may not directly affect to CD68, CD11c and CD163 in NPC." (PMID 34407796, 2021). "The co-expression of MIF and CD74 seems to be important in tumorigenesis, and either MIF or CD74 alone might not be strong tumor biomarkers." (PMID 33542244, 2021). "Hence, MIF-KD tumor cells failed to induce murine RANTES in vivo; confirming that MIF released by tumor cells is the primary chemokine that triggers the release of RANTES from endothelial cells." (PMID 21647415, 2011). "Likewise, no role in tumor progression has been assigned yet to DDT, a protein with homology to macrophage migration inhibitory factor (MIF)." (PMID 17553165, 2007). "Moreover, reducing MIF levels in GBM cells did not alter their proliferation, but when transplanted into an immune competent orthotopic model, resulted in increased host survival and an increase in the number of CD8 T cells in the tumor microenvironment." (PMID 32625208, 2020). "In accordance with MIF and CXCL8, the clinical significance of CCL4 was not consistent, even opposite, in different cancers, suggesting that the biological functions of these cytokines in tumorigenesis and therapy response are complicated and labile and may be tumor type-specific." (PMID 40092701, 2025).
cancer (451 papers, 2004 to 2026). A tumor composed of atypical neoplastic, often pleomorphic cells that invade other tissues. "Collectively, these insights highlight MIF and its associated signaling pathways as potential therapeutic targets in cancer treatment." (PMID 41597203, 2026). "Our findings show that WISP1 induces the expression of MIF, a cytokine known to be linked to pro-tumorigenic and pro-metastatic activities in various cancers." (PMID 41597235, 2026). "As a prognostic biomarker, MIF has been implicated in cancer progression and recurrence, particularly in castration-resistant prostate cancer (CRPC)." (PMID 41159021, 2025). "MIF promotes DNA homologous recombination by activating breast cancer type 1 susceptibility protein, leading to cancer cell resistance to ferroptosis." (PMID 40919133, 2025). "Among the hypoxia-related molecules, MRPS17, CDCHD2, PSMA7, and MIF consistently demonstrated a positive correlation with PEBP1/STK11 co-expression across all cancer types in which a significant association was observed." (PMID 40806276, 2025). "Elevated levels of MIF have been associated with the severity of inflammatory diseases and cancers, making it a potential prognostic tool." (PMID 40092999, 2025). "MIF is associated with cancer occurrence and serves as a link between chronic inflammation and cancer." (PMID 40411322, 2025). "More importantly, high-risk cancer cells were characterized by enhanced MIF signal-sending capacity, which promotes the establishment of an immunosuppressive microenvironment by regulating macrophage function and polarization states." (PMID 41200185, 2025). "Further research is needed to fully elucidate the molecular mechanisms underlying MIF‐mediated signalling and its implications in cancer biology." (PMID 38520216, 2024). "Macrophage migration inhibitory factor (MIF) has been described as a pleiotropic proinflammatory and protumorigenic cytokine implicated in the pathogenesis of cancer and inflammatory diseases." (PMID 39727487, 2024). "The potential of MIF as a biomarker has been recognized, as its elevated levels have been linked to unfavorable outcomes in various types of cancer." (PMID 38238845, 2024). "MIF has been implicated in various aspects of cancer, including cell proliferation, tumorigenesis, and metastasis." (PMID 38520216, 2024). "More precisely, MIF downregulated the interaction between cancer-associated fibroblasts and immune cells including B cells, DCs, myeloid derived suppressor cells, monocytes, NK cells, and T cells via the CD74/CD44 and CXCR2/CXCR4 signaling pathways." (PMID 38638429, 2024). "Despite an overall suppression of macrophage-related pathways, the activities of SPP1 and MIF remained more vigorous, potentially indicating a closer association of these pathways with cancer progression." (PMID 39850883, 2024). "MIF, which is associated with most cancers in all stages, can modify the activation, adherence, and phagocytosis of macrophages." (PMID 38464520, 2024). "A recent meta‐analysis revealed that MIF overexpression is associated with a poor prognosis and lower survival rates in cancer patients." (PMID 38520216, 2024). "Transducing these cells with MIF shRNA caused a decrease in cancer cell proliferation compared with the control." (PMID 36672343, 2023). "Inflammation is one of the main lethal factors in angiogenesis and cancer, which cause DNA damages through several macrophage migration inhibitory factor (MIF) and reactive oxygen species (ROS) and reactive nitrogen species (RNS) production." (PMID 36984763, 2023). "Macrophage migrationinhibitory factor (MIF) is a multifunctionalcytokine and essential signaling protein associated with inflammationand cancers." (PMID 37352470, 2023). "MIF is involved in the cell‐to‐cell immune and inflammatory response regulation by encoding lymphokines linked to inflammatory diseases and cancer." (PMID 37784249, 2023).
cancer (continued). "High levels of macrophage migration inhibitory factor (MIF) in patients with cancer are associated with poor prognosis." (PMID 37067909, 2023). "In cancer, MIF clearly seems to be pathogenic and targeted treatment seems to be less controversial." (PMID 35091838, 2022). "Increasing evidence suggests that abnormal MIF expression is closely associated with different inflammatory diseases and certain cancers." (PMID 35567291, 2022). "High MIF levels are associated with a poor prognosis in multiple cancer types through various mechanisms." (PMID 36703790, 2022). "Macrophage migration inhibitory factor (MIF) is an upstream regulator of innate immunity, but its expression is increased in some cancers via stabilization with HSP90-associated chaperones." (PMID 33542244, 2021). "MIF KO similarly suppressed Pol δ-deficient cancer cell growth, although loss of Pol δ already significantly inhibited MDA-MB-231 cell growth." (PMID 34012010, 2021). "In an analysis of The Cancer Genome Atlas, high MIF and DDT expression were associated with poor prognosis." (PMID 34516577, 2021). "Macrophage migration inhibitory factor (MIF) is a pleiotropic cytokine implicated in the pathogenesis of inflammation and cancer." (PMID 33776775, 2021). "More recent studies also indicate that MIF is implicated in certain forms of cancer phenotypes such as melanoma, glioblastoma, prostate cancers, and neuroblastoma." (PMID 31936865, 2020). "MIF has been implicated in several autoimmune and inflammatory disorders and, recently, it has been related to cancer progression due to the signaling pathways it activates." (PMID 31963754, 2020). "Functional variants ‐173 G > C (rs755622) and ‐794CATT5‐8 (rs5844572) MIF gene have been associated with the risk in several types of cancer, as well as with the increase of soluble levels of MIF and TNFα." (PMID 31978276, 2020). "Our findings agree with recent studies demonstrating that MIF displays pro-tumorigenic activity and has a causal role in the pathogenesis of inflammatory diseases and cancer." (PMID 31557914, 2019). "MIF is a pro-inflammatory protein that plays a significant role in inflammatory pathways, and has been implicated in many cancer phenotypes." (PMID 30728920, 2019). "Experimental and clinical studies show that high levels of MIF are found in almost all types of human cancers and are implicated in seemingly all stages of development of tumors." (PMID 31275738, 2019). "A meta-analysis indicates an association between any C allele in the MIF -173 G/C promoter polymorphism and an increased risk of cancer, particularly for solid tumors." (PMID 29707160, 2018). "Macrophage MIF plays an important role in the inflammatory pathways and is associated with the occurrence of many cancer phenotypes." (PMID 30386232, 2018). "Several cytokines, such as tumor necrosis factor (TNF)-α, interleukins (IL-6, IL-17, IL-12, IL-23, IL-10), transforming growth factor (TGF)-β, and macrophage migration inhibitory factor (MIF) have been linked with both experimental and human cancers." (PMID 29373553, 2018). "In agreement with these oncogenic properties, both experimental and clinical studies have shown that high levels of MIF are found in several types of human cancers and are apparently implicated in all stages of development of the tumors." (PMID 29707160, 2018). "This is in line with previous studies showing that MIF induces secretion of VEGF in several cancer cell lines and that MIF-deficient mice express reduced levels of VEGF in the lungs." (PMID 28179905, 2017). "We conclude that oxMIF is the disease related isoform of MIF in solid tumors and a potential new diagnostic marker and drug target in cancer." (PMID 27636991, 2016).